CDH20 (cadherin 20)
Description:
Cadherins are calcium-dependent cell adhesion proteins. They preferentially interact with themselves in a homophilic manner in connecting cells; cadherins may thus contribute to the sorting of heterogeneous cell types.
Synonyms: CDH7L3; Cdh7
Tractability: Antibody: UniProt places it where antibodies can reach, with medium confidence; UniProt predicts a signal peptide or a membrane-spanning region; its Gene Ontology location is reachable by antibodies, with medium confidence.
Gene: Protein-coding gene on chromosome 18 (61,333,430 to 61,555,779, forward strand). Ensembl gene ENSG00000101542.
Subcellular location: Cell membrane
Gene Ontology:
Molecular function: beta-catenin binding; cadherin binding; calcium ion binding
Biological process: adherens junction organization; calcium-dependent cell-cell adhesion; cell migration; cell morphogenesis; cell-cell adhesion mediated by cadherin; cell-cell junction assembly; cell adhesion; cell-cell adhesion; homophilic cell-cell adhesion
Cellular component: adherens junction; catenin complex; membrane; plasma membrane
Genetic constraint (gnomAD): Loss-of-function variants: 28 observed, 72.12 expected, observed/expected ratio (o/e) 0.39, 90% interval 0.29 to 0.53. The upper end of that interval is the gene's LOEUF score, 0.53, which puts it in group 2 of 6, group 1 being the genes least tolerant of losing a copy. Missense variants: 979 observed, 1,081.3 expected, observed/expected ratio (o/e) 0.91, 90% interval 0.86 to 0.95. Synonymous variants: 468 observed, 423.17 expected, observed/expected ratio (o/e) 1.11, 90% interval 1.02 to 1.19.
Homologues: Orthologues: chimpanzee CDH20 (99% identical), macaque CDH20 (98% identical), pig CDH20 (98% identical), rabbit CDH20 (97% identical), dog CDH20 (97% identical), guinea pig CDH20 (96% identical), mouse Cdh20 (96% identical), rat Cdh20 (96% identical), tropical clawed frog cdh20 (78% identical). Paralogues in human: CDH7 (60% identical), CDH6 (58% identical), CDH10 (57% identical), CDH8 (56% identical), CDH18 (56% identical), CDH11 (55% identical), CDH12 (55% identical), CDH9 (55% identical), CDH22 (52% identical), CDH24 (49% identical), CDH19 (47% identical), CDH5 (39% identical), and 21 more.
Diseases named in the same sentence as CDH20 in open-access papers:
CDH20 is named in the same sentence as 19 diseases in open-access papers, as found by Europe PMC text mining. Sharing a sentence is not in itself a finding about the gene and the disease. The quoted sentences say what the papers report.
breast carcinoma (2 papers, 2013 to 2019). "Previous studies have shown that CDH20 is mutated in several cancers, including esophageal adenocarcinoma, colorectal cancer, cervical cancer, and breast cancer." (PMID 31998642, 2019). "CDH20 encodes a type II classical cadherin which is involved in cell to cell adhesion and its mutation was previously reported in breast cancer." (PMID 23301059, 2013). "Moreover, CDH20 has been identified as a high-frequency mutated gene in breast cancer and colorectal cancer." (PMID 31998642, 2019).
colorectal adenoma (2 papers, 2013 to 2019). An adenoma that arises from the colon or rectum. "First, CDH20 and LAMA3, which are both involved in cell adhesion, were found to be mutated in the colorectal adenoma." (PMID 23301059, 2013).
adenoma (1 paper, 2013). A neoplasm arising from the epithelium. "We found that CDH20 and LAMA3 were mutated in the adenoma while NRXN3 and COL4A6 were mutated in the adenocarcinoma." (PMID 23301059, 2013). "CDH20 and LAMA3 were mutated in the adenoma while NRXN3 and COL4A6 were mutated in the adenocarcinoma from the same patient, suggesting for the first time that genetic alterations in the cell adhesion pathway occur as early as in the adenoma." (PMID 23301059, 2013).
cervical cancer (1 paper, 2019). A primary or metastatic malignant neoplasm involving the cervix. "Although CDH20 mutations have been found in cervical cancer, the effect of aberrant CDH20 expression on the metastasis of cervical cancer is yet unclear." (PMID 31998642, 2019). "Cancer-associated cadherin 20 (CDH20) is a novel identified cadherin that is genetically altered in several types of human cancer, including cervical cancer." (PMID 31998642, 2019). "To address how CDH20/β-catenin suppresses EMT and migration and invasion in cervical cancer cells, we investigated the causal relationship among CDH20, TGF-β, and EMT." (PMID 31998642, 2019). "Previous high-throughput sequencing results indicated that CDH20 is mutated in cervical cancer tissues and has a potential role in cervical disease progression." (PMID 31998642, 2019). "Taken together, these results suggest that CDH20 inhibits migration and invasion by promoting the adhesion of cervical cancer cells." (PMID 31998642, 2019). "In summary, this study provides the first evidence that CDH20 plays important roles in cervical cancer cell migration, invasion, and adhesion." (PMID 31998642, 2019). "First, we detected CDH20 expression in five different cervical cell lines and found that the selected cervical cancer cell lines had lower expression of CDH20 than the cervical epithelial cells (Ect1/E6E7 cells)." (PMID 31998642, 2019). "In the present study, we evaluated the correlation between aberrant expression of CDH20 and tumor progression in clinical cervical cancer samples." (PMID 31998642, 2019). "To further confirm the importance of CDH20 in the presence of β-catenin, we performed rescue experiments in cervical cancer cells." (PMID 31998642, 2019). "In this study, we show that CDH20 was downregulated in clinical cervical cancer samples and its expression correlated with cervical cancer clinical features." (PMID 31998642, 2019). "In this study, we found decreased CDH20 levels in cervical cancer tissues and uncovered that CDH20 is important for cervical cancer cell migration, invasion, and adhesion." (PMID 31998642, 2019). "To verify the important role of CDH20 in cervical cancer cells using another method, we stably overexpressed CDH20 in the Caski cell line." (PMID 31998642, 2019). "We also examined the effects of CDH20 on cervical cancer cell functions in vitro." (PMID 31998642, 2019). "Our results suggest that CDH20 functions as a tumor suppressor in cervical cancer." (PMID 31998642, 2019). "Taken together, our data suggest that CDH20 may act as a tumor suppressor that interacts with β-catenin to inhibit cervical cancer cell migration and invasion via TGF-β/Smad/Snail mediated EMT." (PMID 31998642, 2019). "Altogether, these data suggest that CDH20 was downregulated in cervical cancer and might promote the progression of cervical cancer by enhancing the motility of cancer cells." (PMID 31998642, 2019). "Thus, the results indicated that CDH20 interacts with β-catenin to inhibit cervical cancer cell migration and invasion." (PMID 31998642, 2019). "In line with prior findings, our data showed that CDH20 inhibited cervical cancer cell migration and invasion, and dysregulation of CDH20 caused changes in EMT-related proteins, indicating that CDH20 was associated with EMT in cervical cancer cells." (PMID 31998642, 2019). "A reduced level of CDH20 mRNA was observed in 37 (~77.1%) cervical cancer tissues." (PMID 31998642, 2019). "In light of these observations, we hypothesized that CDH20 inhibited EMT, and further examined whether altering the expression of CDH20 could affect the phenotypes of cervical cancer cell lines." (PMID 31998642, 2019). "CDH20 negatively regulated the migration and invasion of cervical cancer cells." (PMID 31998642, 2019). "Therefore, the results suggest that CDH20 affected both expression and membrane distribution of β-catenin in cervical cancer cells." (PMID 31998642, 2019).
cervical cancer (continued). "To test this assumption, we investigated the role of CDH20 in cervical cancer cell lines." (PMID 31998642, 2019). "Furthermore, the evaluation of clinical samples shows that dysregulation of CDH20 is associated with both metastatic and non-metastatic cervical cancer." (PMID 31998642, 2019). "Moreover, the level of CDH20 protein was negatively correlated with cervical cancer in both nonmetastatic or lymphatic metastatic tumor samples, suggesting that CDH20 was downregulated in cervical cancer." (PMID 31998642, 2019). "Therefore, our study implies that dysregulation of CDH20 may functionally drive the metastasis of cervical cancer." (PMID 31998642, 2019). "Thus, CDH20 might serve as a potential marker and target for the clinical diagnosis and therapy of cervical cancer." (PMID 31998642, 2019). "To explore the exact role of CDH20, we first analyzed the level of CDH20 mRNA in 48 paired cervical cancer and matching non-cancerous adjacent tissue samples." (PMID 31998642, 2019). "Immunohistochemical (IHC) analysis of the paired 48 cases revealed that CDH20 was expressed mainly in the nonmalignant tissues, and the staining was significantly stronger than that in the cervical cancer tissues." (PMID 31998642, 2019).
endometriosis (1 paper, 2017). The growth of functional endometrial tissue in anatomic sites outside the uterine body. "Of these eight loci, three were associated with all endometriosis (LAMC3, CAPN14 and DEFA1), and six with Stage B disease (NAALADL2, NR2C1, C14orf132, FOXP2, CDH20 and LAMC3)." (PMID 28333195, 2017).
esophageal adenocarcinoma (1 paper, 2019). A malignant tumor with glandular differentiation arising predominantly from Barrett mucosa in the lower third of the esophagus. "For instance, a copy-number loss of CDH20 is detected in 41% of esophageal adenocarcinoma tissues." (PMID 31998642, 2019).
lymph node metastasis (1 paper, 2019). "Furthermore, lower CDH20 protein levels were observed to negatively correlate with histologic grade, FIGO stage, and lymph node metastasis." (PMID 31998642, 2019).
melanoma (1 paper, 2025). A malignant, usually aggressive tumor composed of atypical, neoplastic melanocytes. "CDH20 (cadherin 20) has been shown to act as a cancer suppressor, and some cancer cell lines (e.g., melanoma cell line) lack the expression of CDH20." (PMID 39621192, 2025).
osteosarcoma (1 paper, 2019). A usually aggressive malignant bone-forming mesenchymal neoplasm, predominantly affecting adolescents and young adults. "Moreover, analysis of osteosarcoma in Paget's disease reveals that the tumor undergoes loss of heterozygosity in the CDH20 region, which is similar to that of the tumor suppressor E-cadherin." (PMID 31998642, 2019).
schizophrenia (1 paper, 2022). A major psychotic disorder characterized by abnormalities in the perception or expression of reality. "Our expression analysis revealed increased H3K9me2 and decreased expression of CDHR2; decreased H3K9me2, and increased expression of CDH20, suggesting that symptoms typically reported by individuals with schizophrenia may be caused by dysregulation spread throughout the cadherin system." (PMID 36386965, 2022).
tumor (4 papers, 2014 to 2026). "The CDH20 gene encodes a type 2 classical cadherin, which is a calcium dependent cell-cell adhesion glycoprotein and a prime candidate for tumor suppression." (PMID 25071839, 2014). "Some CNAs overlapped between tumor types, others were tumor type-specific; losses of CDH20 and PTEN were observed in both tumor types, whereas amplifications seemed more tumor type-specific, such as EGFR and MAP2K4 in colon cancer and ERBB2 in breast cancer." (PMID 41537310, 2026). "These specific interactions, such as the ones between DLX6-AS1 and DLX6 and between C8orf34-AS1 and CDH20, highlight a direct molecular interplay that may influence tumor behavior in the context of genomic instability." (PMID 40149330, 2025). "Hence, our findings provide direct evidence supporting the hypothesis that CDH20 might be a candidate tumor suppressor gene." (PMID 31998642, 2019). "Compared with the non-metastatic tumor tissues, lower levels of CDH20 protein were observed in the tumors with lymphatic metastasis." (PMID 31998642, 2019).
cancer (3 papers, 2019 to 2025). A tumor composed of atypical neoplastic, often pleomorphic cells that invade other tissues. "This panel included PDGFR-α (platelet-derived growth factor receptor alpha) and CDH20 (cadherin 20); both were significantly upregulated in MSCs compared to cancer cell lines." (PMID 39621192, 2025). "While CDH20 is known to play a critical role in cancer cell migration, its involvement in cell repulsion has not yet been reported." (PMID 40082910, 2025). "CDH20 is involved in cell adhesion and has been reported to be genetically altered in several cancers." (PMID 31998642, 2019). "Although Wnt/β-catenin signaling plays significant roles in the regulation of both EMT and invasive cancer formation, it appears to have no direct association with CDH20-mediated functions in our study." (PMID 31998642, 2019). "We analyzed a group of genes that were upregulated in MSC lines compared to cancer cell lines, including transcription factors (ZBTB16, HAND2, and TWIST1), a cadherin regulating cell adhesion (CDH20), a receptor tyrosine kinase (PDGFR-α), and a negative cell cycle regulator (CDKN2A)." (PMID 39621192, 2025).
psychiatric disorder (1 paper, 2022). A disorder characterized by behavioral and/or psychological abnormalities, often accompanied by physical symptoms. "Cadherin family members CDHR2 and CDH20 are intercellular adhesion molecules associated with psychiatric disorders." (PMID 36386965, 2022).
CDH20 also shares sentences with these, for which no sentence is quoted: adenocarcinoma (1 paper); cervical disease (1); cervical tumors (1); colorectal cancer (1); Obesity (1); Paget disease (1).